CTH (cystathionine gamma-lyase)
Description:
Catalyzes the last step in the trans-sulfuration pathway from L-methionine to L-cysteine in a pyridoxal-5'-phosphate (PLP)-dependent manner, which consists on cleaving the L,L-cystathionine molecule into L-cysteine, ammonia and 2-oxobutanoate. Part of the L-cysteine derived from the trans-sulfuration pathway is utilized for biosynthesis of the ubiquitous antioxidant glutathione. Besides its role in the conversion of L-cystathionine into L-cysteine, it utilizes L-cysteine and L-homocysteine as substrates (at much lower rates than L,L-cystathionine) to produce the endogenous gaseous signaling molecule hydrogen sulfide (H2S). In vitro, it converts two L-cysteine molecules into lanthionine and H2S, also two L-homocysteine molecules to homolanthionine and H2S, which can be particularly relevant under conditions of severe hyperhomocysteinemia (which is a risk factor for cardiovascular disease, diabetes, and Alzheimer's disease). Lanthionine and homolanthionine are structural homologs of L,L-cystathionine that differ by the absence or presence of an extra methylene group, respectively. Acts as a cysteine-protein sulfhydrase by mediating sulfhydration of target proteins: sulfhydration consists of converting -SH groups into -SSH on specific cysteine residues of target proteins such as GAPDH, PTPN1 and NF-kappa-B subunit RELA, thereby regulating their function. By generating the gasotransmitter H2S, it participates in a number of physiological processes such as vasodilation, bone protection, and inflammation (Probable). Plays an essential role in myogenesis by contributing to the biogenesis of H2S in skeletal muscle tissue (By similarity). Can also accept homoserine as substrate (By similarity). Catalyzes the elimination of selenocystathionine (which can be derived from the diet) to yield selenocysteine, ammonia and 2-oxobutanoate (By similarity).
Synonyms: CGL; CSE
Tractability: Small molecule: a structure with a bound ligand is known; a high-quality ligand is known; it has a high-quality binding pocket. PROTAC: ubiquitination databases record sites on it; its protein half-life has been measured; a small molecule that binds it is known.
Target class: Enzyme; Lyase
Safety:
Unwanted effects reported when the protein is acted on. In parentheses: how it was acted on, where the effect was seen, and who reports it.
sinusoidal obstruction syndrome (source: ClinPGx)
sinusoidal obstruction syndrome (SOS) (source: ClinPGx)
Gene: Protein-coding gene on chromosome 1 (70,406,194 to 70,442,771, forward strand). Ensembl gene ENSG00000116761.
Subcellular location: Cytoplasm
Pathways (Reactome):
Metabolism: Cysteine formation from homocysteine; Degradation of cysteine and homocysteine; Metabolism of ingested SeMet, Sec, MeSec into H2Se
Gene Ontology:
Molecular function: cystathionine gamma-lyase activity; identical protein binding; L-cystine L-cysteine-lyase (deaminating); protein binding; pyridoxal phosphate binding; homocysteine desulfhydrase activity; L-cysteine desulfhydrase activity; selenocystathionine gamma-lyase activity
Biological process: cysteine biosynthetic process; hydrogen sulfide biosynthetic process; positive regulation of aortic smooth muscle cell differentiation; protein homotetramerization; protein sulfhydration; protein-pyridoxal-5-phosphate linkage via peptidyl-N6-pyridoxal phosphate-L-lysine; transsulfuration; endoplasmic reticulum unfolded protein response; negative regulation of apoptotic process; positive regulation of canonical NF-kappaB signal transduction; selenium compound metabolic process
Cellular component: extracellular exosome; cytosol; cytoplasm
Genetic constraint (gnomAD): Loss-of-function variants: 36 observed, 44.1 expected, observed/expected ratio (o/e) 0.82, 90% interval 0.62 to 1.08. The upper end of that interval is the gene's LOEUF score, 1.08, which puts it in group 4 of 6, group 1 being the genes least tolerant of losing a copy. Missense variants: 386 observed, 423.8 expected, observed/expected ratio (o/e) 0.91, 90% interval 0.84 to 0.99. Synonymous variants: 131 observed, 150.6 expected, observed/expected ratio (o/e) 0.87, 90% interval 0.75 to 1.01.
Gene-disease validity (ClinGen):
ClinGen rates the evidence that CTH causes each of these diseases.
cystathioninuria (autosomal recessive): Definitive. Cystathioninuria is an autosomal recessive disorder caused by cystathionine gamma-lyase deficiency.
Homologues: Orthologues: chimpanzee CTH (99% identical), macaque CTH (92% identical), rabbit CTH (91% identical), pig CTH (88% identical), rat Cth (84% identical), mouse Cth (84% identical), guinea pig CTH (79% identical), zebrafish cth (75% identical), tropical clawed frog cth (73% identical), dog CTH (71% identical), zebrafish cthl (69% identical), Drosophila melanogaster Cth (60% identical), and 2 more.
Diseases named in the same sentence as CTH in open-access papers:
CTH is named in the same sentence as 101 diseases in open-access papers, as found by Europe PMC text mining. Sharing a sentence is not in itself a finding about the gene and the disease. The quoted sentences say what the papers report.
glioblastoma (11 papers, 2016 to 2025). The most malignant astrocytic tumor (WHO grade IV). "CTH expression in the tumor stroma/microenvironment plays a crucial role for glioblastoma formation and triggers the expression of the GSC marker SOX2 without affecting the tumoral vascular network." (PMID 37300955, 2023). "This study relied on xenografts in immunocompromised mice and did not examine the importance of the tumoral vascular network or more generally, the role of CTH in the tumor stroma cells of glioblastoma." (PMID 37300955, 2023). "Pharmacological (PAG) inhibition of CTH on human glioblastoma cells results to lower Glioblastoma Stem Cell (GSC) formation and lower mRNA expression of stem cell markers (i.e, PROM1, NOX4)." (PMID 37300955, 2023). "Pharmacologic CTH inhibition suppressed glioblastoma invasion, while CTH knockdown slowed glioblastoma invasion in vivo." (PMID 37971886, 2023). "In cancer, CTH is an important regulator of tumor progression by modulating the redox balance of tumor cells and promoting proliferation and metastasis, and its inhibition significantly suppresses the formation of several cancers such as glioblastoma." (PMID 40299448, 2025). "The CTH gene has been studied in various tumors, including lung adenocarcinoma, prostate cancer, hepatocellular carcinoma, and glioblastoma; however, its specific expression in PanNETs remains unknown." (PMID 40217502, 2025). "Meanwhile, inhibition of CTH suppressed the invasive glioblastoma phenotype." (PMID 38299594, 2024). "Whether CTH is able of supporting angiogenesis-related mechanisms during glioblastoma formation remains unknown." (PMID 37300955, 2023). "Since lower levels of tumoral angiogenesis and tumoral macrophage infiltration does not seem to be the main players driving the attenuated glioblastoma formation in the CTH KO mice, we next decided to focus on molecular players driving glioblastoma stem cell (GSC) formation." (PMID 37300955, 2023). "Since CTH is a known inducer of angiogenesis and the vascular network is known to play a crucial role in supporting glioblastoma formation, we wanted first to determine if the substantially smaller tumors observed in the CTH KO were also accompanied by an altered tumor microvascular network." (PMID 37300955, 2023). "Overview of the proposed mechanisms by which CTH might regulate glioblastoma formation." (PMID 37300955, 2023). "Inhibition of CTH could be a new promising target against glioblastoma formation." (PMID 37300955, 2023). "Cystathionine-gamma lyase (CTH) is one of the main Hydrogen Sulfide (H2S) producing enzymes and its expression contributes to tumorigenesis and angiogenesis but its role in glioblastoma development remains poorly understood." (PMID 37300955, 2023). "Glioblastomas, IDH-wildtype, may also exhibit elevated cystathionine due to activation of the transsulfuration pathway to resist ferroptosis, with cystathionine gamma-lyase acting as a metabolic bottleneck." (PMID 41140994, 2025). "A CRISPR metabolic gene screen revealed cystathionine γ-lyase (CTH), which converts cystathionine to the nonessential amino acid cysteine in the transsulfuration pathway, to be essential for glioblastoma invasion." (PMID 37971886, 2023). "Our results show that CTH expressed in the tumor microenvironment supports glioblastoma formation without affecting the tumoral microvascular density." (PMID 37300955, 2023). "Thus, we could hypothesize that the CTH expression in the tumor microenvironment is not primarily responsible for driving macrophage infiltration inside the glioblastoma tumors." (PMID 37300955, 2023). "Therefore, despite the fact that in other cancer models, CTH has been shown to promote tumor angiogenesis, this does not seem to be the case for glioblastoma formation, at least not due to CTH expression in the tumor microenvironment, in this well-established orthotopic immunocompetent mouse GBM." (PMID 37300955, 2023).
glioblastoma (continued). "Our results show that the brain-permeable pharmacological inhibitor of CTH, PAG, is not a cytotoxic drug but can attenuate significantly the GBM cell proliferation and the TGF-β-induced cell migration in mouse glioblastoma cells by an H2S-dependent mechanism." (PMID 37300955, 2023).
Hypertension (10 papers, 2011 to 2025). The presence of chronic increased pressure in the systemic arterial system. "For example, deficiency in CBS or another H2S-synthesis enzyme cystathionine γ-lyase (CSE or CTH) causes hypertension in mice." (PMID 32006269, 2020). "Outcomes of decreased H2S synthesis in the vasculature also involve CTH ubiquitylation and degradation, which are induced by angiotensin II and contribute to hypertension." (PMID 40141131, 2025). "In the mouse cardiovascular system, angiotensin II also induced CTH ubiquitylation and degradation, contributing to hypertension, and these effects were precluded by N-acetylcysteine and the SIRT3 activator honokiol." (PMID 40141131, 2025). "In the studied groups, no significant changes in the expression of CTH gene were found, but there was a tendency to decrease the CTH expression with hypertension and age." (PMID 34069923, 2021). "Cystathionine gamma-lyase (CSE)/hydrogen sulfide (H2S) plays a protective role in cardiovascular diseases including hypertension and ischemia/reperfusion (I/R) injury." (PMID 34335249, 2021). "Mutations in CTH cause the γ‐cystathionase deficiency syndrome cystathioninuria, an autosomal recessive genetic disorder, whereas CSE deletion results in hypertension and atherosclerosis with endothelial dysfunction." (PMID 32755037, 2020). "On the other hand, experimental hypertension induced by constriction of the abdominal aorta upregulated the expression of CTH and increased H2S production by periaortic adipose tissue." (PMID 32585916, 2020). "In a linear regression analysis including age, sex, presence of ICH, hypertension, hyperlipidemia, pWMH, and CTh as independent variables and PSMD as the dependent variable, only higher pWMH (ß = 1.40, 95% CI 1.05–1.75, p < 0.001) was independently associated with increased PSMD." (PMID 37077322, 2023). "In turn, the development of hypertension was observed in mice with knockout CTH gene." (PMID 34069923, 2021). "Disruption of CTH in mice leads to cardiovascular dysfunction and marked hypertension." (PMID 31572179, 2019). "Both proteins, CBS and CTH, were showed in arterial wall of lobar arteries of both normotensive patients and patients with arterial hypertension." (PMID 32585916, 2020).
breast carcinoma (7 papers, 2020 to 2025). "Elevated H2S-producing enzymes have been observed in multiple cancer types, and depletion of CBS or CTH activities results in the suppression of tumor growth in colon cancer, lung cancer, prostate cancer, and breast cancer." (PMID 34207284, 2021). "The study of the UL69 gene in CTH cells could be relevant to understand the molecular mechanisms involved in the development of breast cancer." (PMID 33937031, 2021). "Scientific reports describe the CBS and CTH roles in breast cancer models." (PMID 32041330, 2020). "In addition, induction of CTH expression by signal transducer and activator of transcription 3 (STAT3) signaling facilitates cell proliferation and migration in breast cancer, whereas induction of CTH expression by Wnt/β-catenin pathway stimulates cell proliferation in colon cancer." (PMID 34207284, 2021). "To further demonstrate the pathophysiological relevance of the CTH cell model in vivo, we assessed the expression of the UL69 gene in the genomic DNA obtained from human breast cancer biopsies and paired adjacent healthy tissue." (PMID 33937031, 2021). "Given above, and the fact that CTH expression decreases upon the exposure of the highest SAC concentration, this all may suggest SAC’s beneficial involvement in the breast cancer MCF-7 cell line." (PMID 32041330, 2020). "Moreover, overexpression of miR-27a in breast cancer cells not only attenuates mammosphere formation and survival but also chemosensitizes breast cancer cells by down-regulating glutathione-related NRF2, CTH, and SLC7A11, leading to attenuation of ROS defense system and autophagy." (PMID 40028033, 2025).
cystathioninuria (7 papers, 2010 to 2024). "Although cystathioninuria (OMIM 219500) by CTH deficiency (CTH−/−) is considered a benign biochemical anomaly and rarely found in general clinical settings, its reported incidence is 1/73,000–333,000." (PMID 35055113, 2022). "Several polymorphic mutations on CTH are found in patients with cystathioninuria, and mutation on Q240E exhibits ~70‐fold decrease in its kinetic activity." (PMID 31468690, 2019). "Hereditary cystathioninuria/cystathioninemia due to CTH deficiency has been considered as a benign biochemical anomaly without any striking clinical/pathophysiological manifestations." (PMID 31319489, 2019). "Therefore, patients with silent CTH-deficient cystathioninuria that exist with a low but substantial frequency should be carefully examined; CBS deficiency had been detected with a frequency between 1:200,000 and 1:335,000." (PMID 31319489, 2019).
hyperhomocysteinemia (7 papers, 2019 to 2024). A serious metabolic condition caused by mutations in the MTHFR gene, medications, or nutritional deficiency. "A common mutation (1364T/T) of the cystathionine-γ-lyase (CTH) gene affects the enzyme that converts cystathionine to cysteine in the transsulfuration pathway causing plasma elevation of total homocysteine (tHcy) or hyperhomocysteinemia—a strong and independent risk factor for cognitive loss and AD." (PMID 30646578, 2019). "Cystathionine Gamma-Lyase (CTH), a protein-coding gene, is primarily linked to hyperhomocysteinemia and cystathionuria." (PMID 38388661, 2024). "Depletion of CTH results in oxidative stress, vascular defects, abnormal stress responses, and hyperhomocysteinemia." (PMID 33522955, 2021). "Deficiency of the metabolic enzymes [e.g., betaine homocysteine methyltransferase (BHMT), cystathionine β-synthase (CBS), and cystathionine γ-lyase (CTH)] involved in these two pathways can lead to hyperhomocysteinemia." (PMID 34393786, 2021). "The most common genetic causes of hyperhomocysteinemia are mutations of the methylenetetrahydrofolate reductase (MTHFR) and cystathionine gamma-lyase (CTH) genes." (PMID 31443445, 2019). "Previous studies have found that hypermethylation of the CTH promotor in hyperhomocysteinemia in mice can lead to the decrease of CTH expression, which in turn prevents homocysteine from being catabolized and causes vascular endothelial cells injury, eventually results in CAD." (PMID 33033488, 2020). "Polymorphisms of the CTH and MTHFR genes are common genetic causes of hyperhomocysteinemia." (PMID 30646578, 2019). "Plasma elevation of total homocysteine (tHcy) or hyperhomocysteinemia may result from congenital deficiency of cystathionine β-synthase (CBS) leading to homocystinuria, or more frequently from polymorphisms of the cystathionine γ lyase (CTH) gene (OMIM *607657; EC 4.4.1.1)." (PMID 30646578, 2019).
prostate carcinoma (7 papers, 2019 to 2025). A carcinoma that arises from epithelial cells of the prostate gland. "Increased CTH (Cystathionine Gamma-Lyase) expression in patients with advanced prostate cancer is associated with poor survival, and H2S produced by CTH promotes the progression and metastasis of prostate cancer through the IL-1β/NF-κB signaling pathway." (PMID 33718182, 2021). "An insufficient concentration of H2S has been described, for example, in Alzheimer’s or Huntington’s disease, whereas overexpression of hydrogen sulfide-producing enzymes, such as CTH, is often associated with the presence of testicular neoplasms, embryonic carcinoma, or prostate cancer." (PMID 39324123, 2024). "CTH, another H2S-producing enzyme, is demonstrated as being up-regulated in several different cancer types, including prostate cancer, gastric cancer, and melanoma cells." (PMID 34207284, 2021). "Clinical data further reveal that the expression of CTH is elevated in late‐stage prostate cancer patients, and higher CTH expression correlates with poor survival from The Cancer Genome Atlas (TCGA) prostate cancer RNA‐seq datasets." (PMID 31468690, 2019). "Together, our findings provide evidence that CTH generated H2S promotes prostate cancer progression and metastasis through IL‐1β/NF‐κB signaling pathways." (PMID 31468690, 2019). "This suggests that CTH and H2S could be potential therapeutic targets in intervening in prostate cancer progression." (PMID 39324123, 2024). "In prostate cancer, overexpression of CTH increased H2S production leads to the activation of nuclear factor-κB (NF-κB)-mediated interleukin 1β (IL-1β) signaling, resulting in the enhanced cell invasion, angiogenesis, lymphangiogenesis, tumor growth, and metastasis in prostate cancer." (PMID 34207284, 2021). "This study further indicates that knocking down CTH decreased metastasis, an effect that, as expected, was reverted by overexpressing CTH, indicating a pro-tumoral and pro-metastatic role of cysteine catabolism and H2S production in prostate cancer." (PMID 34150624, 2021). "However, some authors have described that excessive levels of CTH/H2S in the prostate, on the contrary, may promote prostate cancer progression and that their inhibition leads to suppression of tumor growth." (PMID 39324123, 2024). "Moreover, the detection of elevated CTH/H2S levels could help early prostate cancer detection." (PMID 39324123, 2024). "By using xenograft orthotopic implantation of prostate cancer PC3 cells and subsequently comparing bone metastatic with primary tumor‐derived cancer cells, we find that H2S‐producing enzyme cystathionine γ‐lyase (CTH) is upregulated in bone‐metastatic PC3 cells." (PMID 31468690, 2019). "DU145 line was originally derived from brain, and not bone, metastasis 43, and the expression level of CTH was much lower in DU145 cells, as compared to other prostate cancer lines (Fig EV1C)." (PMID 31468690, 2019).